PSAP (prosaposin)
Diseases named in the same sentence as PSAP in open-access papers (continued):
Sharing a sentence is not in itself a finding about the gene and the disease.
cancer (22 papers, 2010 to 2025). A tumor composed of atypical neoplastic, often pleomorphic cells that invade other tissues. "In summary, PSAP emerges as a significant molecule across diverse cancer types, demonstrating dual potential as a diagnostic/prognostic biomarker and a therapeutic target." (PMID 40801564, 2025). "This positions PSAP as a compelling candidate for further development in cancer diagnostics and targeted therapies." (PMID 40801564, 2025). "Collectively, the evidence positions PSAP as a versatile pan-cancer biomarker with tissue-specific role in oncogenesis and therapeutic potentials." (PMID 40801564, 2025). "Koochekpour identified PSAP as an androgen regulator that promotes cancer calls (LNCaP) growth, migration, and invasion via upregulation of androgen receptors (ARs) and their target genes (e.g., Prostate-Specific Antigen, PSA)." (PMID 40801564, 2025). "SAP (P07602, prosaposin) is a mitochondria protein that plays a critical role in sphingolipid and cancer metabolism (Zhang." (PMID 36743215, 2023). "All these studies demonstrate that different cancer cell types express and secrete PSAP, which can affect solid tumor growth and progression by a variety of ways." (PMID 36359323, 2022). "Various studies have also investigated the functional roles of secreted PSAP in cancer growth and metastasis reporting its effects on different cancer cell types." (PMID 36359323, 2022). "Dermcidin (DCD), ezrin (EZR), and prosaposin (PSAP) are also hyper-secreted in both R273H- and R175H-driven secretome samples and they promote cancer progression." (PMID 32526853, 2020). "PSAP is a conserved glycoprotein with multiple functions and it is involved in the development of cancers." (PMID 32526853, 2020). "PSAP is a secreted protein, and has been reported as a protective factor in cancer and brain diseases." (PMID 29481576, 2018). "In a variety of cancers, these 4 up-regulated genes (DNAJB1, MCU, MPRIP and PSAP) have been reported to be related to drug-resistance processes, cell death, cancer invasion and metastasis." (PMID 29285248, 2017). "Although the exact role of the interaction between PSAP and proCath-D in cancer cells remains unclear, it may be involved in lysosomal targeting, protease clearance, or the growth-stimulating action of these two proteins." (PMID 40801564, 2025). "In tumors and cancers, PSAP affects the development of a variety of cancers and tumors." (PMID 40801564, 2025). "Researchers used the TMT label method to identify glycoproteins from cancer cells and found that prosaposin could suppress immune cell infiltration, resulting in the promotion of cancer." (PMID 36743215, 2023). "The fact that PSAP is frequently overexpressed in human malignant cells warrants further investigation of its role in carcinogenesis and in invasive and metastatic progression of cancer cells." (PMID 20132547, 2010). "The cancer cell modules (I) of the two samples are characterized by distinct marker genes, i.e., PMEL, ATP1A1, and SPP1 in sample 1 whereas S100B and PSAP in sample 2, in line with previous studies." (PMID 40033360, 2025). "Moreover, we found PSAP, like HSAD1, which was identified as a prognostics gene in OVCA and served as hub genes for all four cancer types." (PMID 41370198, 2025). "Based on the findings presented in this report, we predict that therapeutic strategies, which augment PSAP activity and inhibit PRSS2 binding to LRP1 could hold tremendous therapeutic potential for cancer patients." (PMID 36575174, 2022).
neurodegenerative disease (10 papers, 2018 to 2026). A disorder of the central nervous system characterized by gradual and progressive loss of neural tissue and neurologic function. "Experimental models of neuronal injury resulted in increased PSAP levels in neurons; further, increased or decreased PSAP levels have been implicated in the development of many neurodegenerative diseases." (PMID 41438692, 2026). "Pharmacological stabilization of PSAP interactions with progranulin has shown promise in neurodegenerative disease models." (PMID 41627451, 2026). "This study revealed that the five biomarkers, GLB1, ARSB, ASAH1, HEXB, and PSAP are all enriched in the lysosomal, chemokine, oxidative phosphorylation, and neurodegenerative disease pathways." (PMID 40534738, 2025). "Disrupted PSAP trafficking may lead to amyloid protein aggregation with implications for neurodegenerative diseases." (PMID 41627451, 2026). "For example, Tian and colleagues discovered through combinatorial CRISPRa/i screens that prosaposin (PSAP) deficiency could result in redox imbalance and neuronal ferroptosis linked to neurodegenerative disease." (PMID 35487213, 2022). "The significance of PSAP in neurodegenerative diseases is just being appreciated." (PMID 31864418, 2019). "Since PSAP and GRN are both lysosomal genes, we hypothesize that biallelic rare variants of these genes are causing severe rare diseases, while the monoallelic rare variants may play role in the development of common neurodegenerative diseases." (PMID 35752680, 2022). "Thus, PSAP may serve as a potential target for treating AD-related neurodegenerative diseases." (PMID 40801564, 2025). "Increased PGRN expression levels have also been observed in some neurodegenerative diseases, regardless of PSAP reduction or overexpression." (PMID 41438692, 2026). "PSAP and PGRN have been recognized as playing a vital role in neurodegenerative diseases." (PMID 36233357, 2022).
infection (4 papers, 2020 to 2025). The state of being infected such as from the introduction of a foreign agent such as serum, vaccine, antigenic substance or organism. "Other proteins with increasing abundance over the course of infection common in both species at d84 vs. d0 (foxes) or d75 vs. d-7 (dogs) were, among others, fibulin 2, interleukin enhancer-binding factor 2, prosaposin, and phosphoglycerate mutase." (PMID 34832667, 2021). "Sortilin is upregulated during infection of macrophages with mycobacteria and is required for the delivery of both prosaposin and Asm from the Golgi complex to phagosomes." (PMID 33153072, 2020).
adenocarcinoma (3 papers, 2011 to 2025). A common cancer characterized by the presence of malignant glandular cells. "In primary adenocarcinoma of the urethra in the prostate department, the typical glandular structure of follicular adenocarcinoma was not seen in the mucus, and immunohistochemical techniques also showed negative PSA and PSAP." (PMID 40896436, 2025).
neurological disorders (2 papers, 2025). "In neurological disorders, PSAP acts as a neurotrophic factor influencing nerve cell survival and synapse growth, and its dysfunction is associated with a variety of diseases." (PMID 40801564, 2025).
PSAP also shares sentences with these, for which no sentence is quoted: frontotemporal dementia (3 papers); pancreatic cancer (3); brain disease (2); gastric cancer (2); lung (2); Multiple sulfatase deficiency (2); pulmonary hypertension (2); adenocarcinoma in situ (1); asthma (1); autism spectrum disorder (1); bacterial infection (1); bipolar disorder (1); bladder adenocarcinoma (1); cardiovascular diseases (1); cholangiocarcinoma (1); chronic lymphocytic leukemia (1); clear renal cell carcinoma (1); corticobasal degeneration (1); dementia (1); diffuse large B-cell lymphoma (1); Encephalopathy (1); fibromatosis (1); Gorlin syndrome (1); hepatocellular carcinoma (1); Intellectual disability (1); intervertebral disk degenerative disorder (1); leiomyosarcoma (1); Lipid storage disease (1); lipidosis (1); lymph node metastases (1).
A further 36 diseases each share a sentence with PSAP in 1 paper.